KRAS (KRas proto-oncogene, GTPase)
Diseases named in the same sentence as KRAS in open-access papers (continued):
Sharing a sentence is not in itself a finding about the gene and the disease.
Lynch syndrome (22 papers, 2010 to 2025). An autosomal dominant hereditary neoplastic syndrome characterized by the development of colorectal carcinoma and a high risk of developing endometrial carcinoma, gastric carcinoma, ovarian carcinoma, renal pelvis carcinoma, and small intestinal carcinoma. "A therapeutic effect was observed irrespective of the degree of PD-L1 expression, the presence of the BRAF/KRAS mutations, or the presence of Lynch syndrome." (PMID 37599324, 2023). "BRAF and KRAS were mutated in 16% and 35% of patients, respectively; 28% of patients had PD-L1 positive tumors and 31% had Lynch syndrome." (PMID 28635639, 2017). "In this present study, germline testing was performed on 16 patients, revealing 8 cases of Lynch syndrome (7 of which harbored KRAS mutations, 87.5%), 1 case of Lynch-like syndrome (carrying a KRAS mutation), and 7 cases of sporadic CRC (5 with KRAS mutations, 71.4%)." (PMID 40818457, 2025). "In addition, previous studies have demonstrated that patients with Lynch syndrome or Lynch-like syndrome exhibit a higher prevalence of KRAS mutations compared to those with sporadic tumors." (PMID 40818457, 2025). "al, focusing on genetic tests of Lynch syndrome (LS) and KRAS mutation tests." (PMID 30256829, 2018). "So we could not calculate the precise frequency of KRAS mutations in hereditary CRCs, however, it is sure that the Lynch syndrome-related CRC in our study showed preferentially KRAS mutations." (PMID 26042813, 2015). "However, KRAS mutations are significantly more frequent in Lynch syndrome-related CRC than that in sporadic MSI-H CRCs." (PMID 26042813, 2015). "The frequency of KRAS mutations in Lynch syndrome-related CRC and sporadic CRC is almost the same." (PMID 26042813, 2015). "Therefore, the higher proportion of KRAS mutations observed in this study may be attributed to ethnic variations, a relatively higher prevalence of Lynch syndrome or Lynch-like syndrome, and sampling errors." (PMID 40818457, 2025). "Lynch syndrome and Lynch-like syndrome CRC frequently harbor not only activating ERBB2 mutations but also specific mutational patterns in PIK3CA and KRAS." (PMID 29849630, 2018). "KRAS mutations were found in 22 (31%) patients, whereas mutation in BRAF was noted in only one case of genetically confirmed Lynch syndrome." (PMID 19935791, 2010). "BRAF V600E mutations are overrepresented in dMMR tumors and can be used to rule out Lynch syndrome, while KRAS mutations (in codons 12 or 13) are inversely correlated with dMMR status." (PMID 30005666, 2018). "Objective responses were observed regardless of PD-L1 expression, BRAF and KRAS mutation status, or the presence of Lynch syndrome." (PMID 28635639, 2017). "Interestingly, patients with Lynch syndrome-associated CRC, representing only 2–3% of all CRC patients, are also found to have a higher frequency of KRAS mutation, yet they generally show a favourable clinical outcome." (PMID 19935791, 2010). "Similarly, the presence of a history of Lynch syndrome or the BRAF or KRAS mutation did not seem to affect response to immunotherapy." (PMID 32090113, 2020). "Since biomarker testing was mostly relevant for patients considered for anti-EGFR therapy (KRAS, NRAS) or younger patients (MMR testing for Lynch syndrome or BRAF testing for prognostication), it is possible that more young and fit patients with mCRC were tested." (PMID 37071802, 2023). "Unfortunately, data on sporadic mismatch repair deficiency, germeline-mutation prompted Lynch Syndrom, BRAF/KRAS/NRAS mutations, or any family history can not be ascertained from the SEER data." (PMID 27464835, 2016).
diabetes (21 papers, 2013 to 2026). "The genistein concentration was higher among participants with older age, a history of diabetes or cardiovascular disease and blood drawn before surgery, while luteolin concentration is higher among those with KRAS mutations." (PMID 30871032, 2019). "Their findings indicated that patients with metastatic CRC and KRAS mutations and co-occurring diabetes who received metformin experienced a significantly longer median survival (an additional 37.8 months) than those treated with other blood sugar-lowering drugs alongside standard systemic therapy." (PMID 40649818, 2025). "Cigarette smoking and unhealthy diet are additionally associated with abnormal metabolic parameters such as hypertension, dyslipidemia, and presence of diabetes mellitus, suggesting that KRAS mutational status may be related to metabolic parameters." (PMID 25158139, 2014). "This review synthesizes current understanding of post-translational modifications (PTM) dynamics in diabetes-associated PDAC, with emphasis on their role in modulating oncogenic pathways such as KRAS-MAPK and PI3K-AKT." (PMID 42193016, 2026). "The only difference between the two arms that reached statistical significance is the incidence of diabetes mellitus, with 18% of the patients in the KRAS wild-type group and only 8% of the patients in the KRAS-mutant group also diagnosed with diabetes." (PMID 37761297, 2023). "Age, sex, performance status, planned chemotherapy, prior adjuvant chemotherapy, assigned treatment arm, KRAS status, tumor sidedness, plasma albumin, diabetes, BMI, and fasting status." (PMID 37485272, 2023). "However, we did note a significant difference in the incidence of diabetes mellitus, with 18% of patients in the KRAS wild-type group and only 8% of patients in the KRAS-mutant group having diabetes." (PMID 37761297, 2023). "Patients with KRAS-mutant CRC: these patients, particularly those with diabetes, appear to significantly benefit from metformin." (PMID 40649818, 2025). "Likewise, it has been hypothesized that patients with diabetes have a higher chance of developing a KRAS mutation; however, this study does not show a significant difference between the diabetic and non-diabetic groups." (PMID 36479258, 2022). "Clinical-pathological data, including age, gender, BMI, hypertension, diabetes, pre-CRC diagnosis serum lipid levels and KRAS status were recorded." (PMID 32594310, 2020).
clear cell carcinoma (20 papers, 2010 to 2025). "The patient carried a typical genomic profile of clear cell carcinoma including mutations in KRAS, PPP2R1A, and PIK3R1." (PMID 38686193, 2024). "In our study, we were able to identify KRAS mutations in patients with endometrioid and clear cell carcinomas." (PMID 33947352, 2021). "Histologically, type I tumors would consist of low-grade micropapillary serous carcinoma, mucinous, endometrioid, and clear cell carcinomas and would be associated with mutations in KRAS, BRAF, PTEN, and beta-catenin." (PMID 22581446, 2012). "KRAS actionability was 16, 18 and 13% in patients with high-grade serous, endometrioid and clear cell carcinomas, respectively, whereas MEK1/2 actionability was 30, 27 and 13%." (PMID 33947352, 2021). "KRAS mutations have been identified in 10–30% of endometrioid endometrial carcinomas while some investigators have reported an almost complete absence of KRAS mutations in serous and clear cell carcinomas of endometrium." (PMID 20368795, 2010). "MYC is an oncogenic downstream target of KRAS and IL6-JAK-STAT signaling and therefore we correlated the expression of MYC and RASSF10 in primary renal papillary cell carcinoma and clear cell carcinoma." (PMID 32047266, 2020).
seminoma (20 papers, 2013 to 2026). A radiosensitive malignant germ cell tumor found in the testis (especially undescended), and extragonadal sites (anterior mediastinum and pineal gland). "In patient SP2, the KIT mutation was concordant in the right and left synchronous seminomas, while in patient SP7, the KRAS mutation was concordant in the right and left synchronous seminomas." (PMID 40358182, 2025). "One seminoma had a KRAS copy number variant, which co-existed with a KIT p.N822K missense mutation (TGCT-7)." (PMID 41009531, 2025). "Two other variants, also on the KRAS gene codon 12 (G12R and G12D), were observed in seminoma cases." (PMID 37007070, 2023). "Several genome wide studies has been conducted in GCTs: in 4–31% of seminomas, and up to 14% of non-seminomas, driver mutations were detected in three genes (KRAS, NRAS and KIT)." (PMID 36860862, 2023). "We demonstrate clear association in seminomas of CN-Sig-1 with KRAS/NRAS/KIT-mutation, a phenomenon also observed in HGSOC27." (PMID 32366847, 2020). "CBL copy number negatively correlated with KIT protein expression for most tumors; however, seminomas with KIT or KRAS mutations maintained high protein levels of KIT regardless of CBL copies, apparently escaping CBL regulation." (PMID 29898407, 2018). "Seminomas can also exhibit c‐Kit mutations or KRAS mutations." (PMID 41384700, 2026). "In addition, KRAS mutations were found in two EC, four seminoma, two MMGCT, and two YST, and NRAS mutations in one seminoma and one YST." (PMID 37149691, 2023). "KIT and KRAS mutations are reported more frequently in seminomas when compared with non-seminomas." (PMID 37007070, 2023). "These genes were exclusive to seminomas except for one KRAS mutation in an NSGCT with 30% seminoma." (PMID 29898407, 2018). "A recent analysis of the Cancer Genome Atlas demonstrated that KIT, KRAS, and NRAS gene variants were observed only in seminoma, while gene variants in B3GNT8, CAPN7, FAT4, GRK1, TACC2, and TRAM1L1 occurred only in embryonal carcinoma." (PMID 41426877, 2025). "The singleton missense gain of function variant (p.E1051K) identified in PIK3CB was observed in two seminoma samples (TGCT-2 and TGCT-3), where it co-existed with either KIT (p.N822K) or KRAS (p.G12R) mutations." (PMID 41009531, 2025). "Our analysis did not reveal a single distinct mutation or hotspot specific to seminoma, consistent with previous studies that highlight a polygenic model with KIT and KRAS as frequent drivers." (PMID 41154418, 2025). "In summary, analysis of AACR Project GENIE data sheds light on a distinct seminoma genomic profile characterized by recurrent mutations in KIT, KRAS, and MTOR, as well as focal copy number alterations in CDKN1B, KRAS, CCND2, and H3F3C." (PMID 41154418, 2025). "The only oncogene identified within cyclic amplicon structures, including ecDNA in one instance, was KRAS, and only in seminomas." (PMID 39461959, 2024). "In conclusion, the increase in the number of copies of the KRAS gene is a very frequent event in TGCT, and non-seminomas are most highly associated with a higher rate of this amplification." (PMID 37007070, 2023). "Non-seminoma cases showed a non significant trend of greater variation in the number of copies of the KRAS gene, when compared to seminoma cases (47.1% vs 33.3%; p = 0.160), and none of the cases showed loss of copy number." (PMID 37007070, 2023). "Association with seminoma was found for mutations in KIT, KRAS and NRAS and for putative oncogenic driver genes CBL, RAC1, PIK3CA, and CTNNB1 (analysed jointly due to lower frequency), p = 3.33 × 10−10, p = 1.41 × 10−6, p = 0.002, p = 0.009, respectively." (PMID 32366847, 2020).
seminoma (continued). "In contrast KRAS was included in the higher focal 12p amplicon of the 3.2N population that was only detected in the primary seminoma tissue." (PMID 30870501, 2019). "The number of expressed CT genes was significantly higher in seminomas (P = 3.48 × 10−13) which were characterized by frequent mutations in driver genes (KIT, KRAS and NRAS)." (PMID 31070303, 2019). "Seminomas with increased copies of KRAS (Chr 12) were more likely to have wild-type KIT (t test p = 0.0007)." (PMID 29898407, 2018). "Three clusters, including KRAS signaling and immune infiltration, showed enriched activity in seminomas." (PMID 29898407, 2018). "Somatic mutation of only three genes achieved significance—KIT, KRAS, and NRAS—exclusively in samples with seminoma components." (PMID 29898407, 2018). "We also identified a subset of pure seminomas defined by KIT mutations, increased immune infiltration, globally demethylated DNA, and decreased KRAS copy number." (PMID 29898407, 2018). "Of the six seminomas with mutations in both KIT and KRAS/NRAS, four were in men with a history of cryptorchidism (odds ratio = 7.3 [95% confidence interval 1.2–45.0]), all in the ipsilateral testicle." (PMID 29898407, 2018). "RAS mutations clustered at known mutation hotspots and mutations in KRAS and NRAS co-existed in only one seminoma." (PMID 29898407, 2018). "KIT mutant seminomas had lower-level copy number levels and gene expression of KRAS than either KIT WT seminomas or NSGCTs." (PMID 29898407, 2018). "Several genomewide studies suggested driver mutations in only three genes (KIT, KRAS, and NRAS) in 4–31% of seminoma, and up to 14% of non-seminoma patients." (PMID 30547014, 2018). "Despite the larger cohort, all but one of the KRAS somatic mutations in that study were exclusive to seminomas, whereas we identified six KRAS alterations in non-seminomatous TGCTs." (PMID 41009531, 2025). "KRAS (STM: > 70%; GCT: 16%) and KIT (STM: 30%; GCT: 14%) were the most amplified or missense mutated genes in the GCT cohort with the majority being mutated in seminomas." (PMID 37726478, 2023). "The findings of KRAS copy number gain might be explained due to the gain of the 12p isochromosome, commonly found in almost all TGCTs, especially in non-seminomas." (PMID 37007070, 2023). "Mutations in the KRAS gene were identified more frequently among seminomas when compared to non-seminomas, and four different variants were observed in five TGCT cases." (PMID 37007070, 2023). "We were not able to identify statistical differences between seminomas and non-seminomas regarding KRAS copy number gain, and none of our cases had loss of copy number." (PMID 37007070, 2023). "These tumours show a low rate of mutations compared to common cancers, which would make the prediction of mutations by AI more challenging, although somatic mutations of the KIT gene and its downstream mediators encoded by the KRAS and NRAS genes have shown significance in seminoma." (PMID 33809521, 2021). "Rather than a mere passenger effect, the focal amplification and upregulation of KRAS in these wildtype seminomas may instead reflect an active alternative mechanism by which RAS signalling has been increased." (PMID 32366847, 2020). "After correction for lymphocytes, the remnant methylation is absent in a subgroup of seminomas that are highly enriched for KIT/KRAS mutations (p < 0.0001), suggesting an essentially complete lack of DNA methylation in this subset." (PMID 29898407, 2018). "However, in patients SP4 and SP5, both KIT and KRAS mutations occurred in the right but not in the left synchronous seminomas." (PMID 40358182, 2025).
seminoma (continued). "In contrast, seminomas exhibited higher activity in INTERFERON_RESPONSE, SPERMATOGENESIS, and KRAS_SIGNALING pathways, reflecting their undifferentiated, germ-cell-like state." (PMID 40568177, 2025). "While WGD was typically among the earliest events in TGCTs, a subset of seminomas (N=25, 17.4%) harbored driver mutations in KIT, KRAS, NRAS, or PIK3CA prior to WGD, irrespective of WGD timing." (PMID 40568177, 2025). "Through adjusted analysis, we delineate independent association with seminoma histology for mutations in KIT, KRAS, NRAS and Pi3K/MTOR pathway gene sets and, independent of histology, association of KIT mutation with platinum sensitivity." (PMID 32366847, 2020). "Gene signatures downstream of KIT signaling such as AKT, PI3K, KRAS, and JAK/STAT were high in seminomas, regardless of KIT or KRAS mutation status." (PMID 29898407, 2018). "Notably, ecDNA contributed to amplification of oncogenes including KRAS (5 seminomas), KIT (1 seminoma), and MDM2 (1 seminoma, 2 non-seminomas)." (PMID 40568177, 2025). "Notably CN-Sig-6, which reflects high copy number states from focal amplification, was particularly high in seminomas with (i) increased 12p copy number, (ii) KRAS copy number and/or, (iii) KRAS mRNA expression (without KIT/KRAS/NRAS mutations)." (PMID 32366847, 2020).